INS (insulin)
Diseases named in the same sentence as INS in open-access papers (continued):
Sharing a sentence is not in itself a finding about the gene and the disease.
Alzheimer disease (continued). "Human studies in patients with mild cognitive impairment and Alzheimer’s disease have shown that administration of some antidiabetic medications, such as intranasal insulin, metformin, incretins, and thiazolidinediones, can improve cognition and memory." (PMID 35563031, 2022). "TUDCA improved glucose tolerance and insulin sensitivity in streptozotocin-induced model of Alzheimer’s disease." (PMID 35800441, 2022). "Studies have shown that such inflammation and impaired insulin signaling contribute to the development of Alzheimer's disease (AD)." (PMID 35173531, 2022). "The large amount of evidence on the existence of insulin resistance in the brain during Alzheimer’s disease has led to the description of this disease as “type 3 diabetes”." (PMID 36499613, 2022). "This disconnect is also found in patients with Alzheimer's disease, who tend to have elevated plasma insulin but reduced CSF insulin levels." (PMID 36244663, 2022). "Intranasal insulin (INI) has shown promise as a treatment for Alzheimer’s disease (AD) in pilot clinical trials." (PMID 35079029, 2022). "A lot of studies have shown that dysfunction of insulin signaling forms the core of neurodegeneration in Alzheimer’s disease (AD)." (PMID 35739484, 2022). "By binding to its receptor, insulin activates signaling whose defect plays a role in brain dysfunction, leading to neurodegenerative diseases, especially Alzheimer’s disease (AD)." (PMID 35741464, 2022). "Alzheimer’s disease is the most common form of neurodegenerative disease, and increasing evidence shows that insulin signaling has crucial roles in AD initiation and progression." (PMID 35741643, 2022). "Growing evidence implicates abnormal insulin signaling in the pathogenesis of Alzheimer’s disease (AD), a neurodegenerative condition whose fundamental feature is β-amyloid (Aβ) and tau protein deposition in the brain." (PMID 35875664, 2022). "Due to space constraints and article scope,we only briefly touch on some of the interesting nodes identified and ranked inSemNet version 2 using Alzheimer’s disease (AD) as the target node andhypothyroidism and insulin as source nodes of interest." (PMID 35936510, 2022). "The main constituents, harmine and harmaline, have displayed therapeutic efficacy against Alzheimer’s disease (AD); however, the P. harmala potential on sensitizing central insulin to combat AD remains to be clarified." (PMID 34103557, 2021). "GHSR1a interacting proteins do, however, represent a potentially exciting new target for appetite regulation, Alzheimer’s disease, insulin secretion, and inflammation." (PMID 34663757, 2021). "Some relationship between abnormal cholesterol content and impairment of insulin/insulin-like growth factor I (IGF-1) signaling has been reported in the pathogenesis of Alzheimer's disease (AD)." (PMID 34671194, 2021). "The following search terms were used: anesthesia, delayed neurocognitive recovery, postoperative neurocognitive disorder, intranasal insulin, Alzheimer’s disease, and Parkinson’s disease." (PMID 33799976, 2021). "Brain insulin signaling is involved not only in brain homeostatic processes but also neuropathological processes such as cognitive decline and Alzheimer's disease." (PMID 33845179, 2021). "Nevertheless, it has been reported that orally administered RJ has ACh-like effects, such as improvement of Alzheimer’s disease, vasodilation induced by nitric oxide production, and induction of insulin secretion." (PMID 34444696, 2021). "PICRUSt analysis showed that the Alzheimer’s disease (AD) and insulin signaling pathway were mainly enriched in 15-week-old ZDF rats." (PMID 34485269, 2021). "Agonists of PPARδ affect energy homeostasis, anti-inflammation and insulin sensitivity and present an attractive target in Alzheimer’s disease pathogenesis." (PMID 34428743, 2021).
Alzheimer disease (continued). "In fact, DM and neurodegenerative disease such as Alzheimer's disease (AD), share common elements such as insulin resistance, altered glucose metabolism, amyloid aggregation and inflammatory response." (PMID 34093866, 2021). "Using an experimental approach to modeling Alzheimer’s disease, new molecular mechanisms of the dysregulation of insulin signaling in the amygdala in connection with the processes of neuroinflammation were investigated." (PMID 34769018, 2021). "Dysregulation of insulin and glucose processing in the CNS is characteristic of aging as well as age-related neurodegenerative diseases (e.g. Alzheimer’s Disease, AD; Parkinson’s Disease, PD)." (PMID 33472174, 2021). "While these and other approaches contribute importantly to advancing science, research on insulin signaling and resistance in human brain tissue is needed to better understand uniquely human conditions such as Alzheimer’s disease (AD) dementia." (PMID 33858515, 2021). "The use of intranasally administered insulin for the treatment of patients with Alzheimer’s disease and mild cognitive deficits leads to a significant improvement in their cognitive functions (see, for example,)." (PMID 34769198, 2021). "Thirdly, multiple pathological studies showed that insulin and Alzheimer's disease share many common lesions in the brain, such as beta-amyloid plaques, amylin-Aβ plaques, hyper-phosphorylated tau protein, and brain atrophy, especially in the hippocampus." (PMID 34877187, 2021). "The observed Aβ effect on insulin-mediated dynamics of the fEPSP amplitudes also correlates with the data described in the literature and fits into the theory of insulin resistance in neurodegenerative diseases such as Alzheimer’s disease." (PMID 34769018, 2021). "Intranasal insulin treatment improved memory and learning in a rat amyloid-beta model of Alzheimer’s disease." (PMID 34108878, 2021). "Intranasally administered insulin has shown promise in both rodent and human studies in Alzheimer's disease; however, both effects and mechanisms require elucidation." (PMID 34101779, 2021). "The most upregulated gene [largest positive log2 fold-change (Log2FC)], Ide, encodes an insulin-degrading enzyme that is known to degrade the B chain of insulin and amyloid beta, suggesting a role in Alzheimer's disease." (PMID 34137816, 2021). "We also measured insulin in the brain amygdala to analyze how its expression level changes when modeling Alzheimer’s disease in NLRP3 knockout mice." (PMID 34769018, 2021). "Several clinical studies have tested the efficacy of insulin‐sensitizing drugs for cognitive enhancement in Alzheimer's disease (AD) patients, as type 2 diabetes (T2D) is a well‐recognized risk factor for AD." (PMID 33382528, 2021). "Type 3 diabetes (T3D) accurately reflects that dementia, e.g., Alzheimer’s disease, represents insulin resistance and neurodegeneration in the brain." (PMID 33670473, 2021). "Intranasal insulin treatment for 12 months reduced white matter hyperintensity volume progression and supports insulin's potential as a therapeutic option for Alzheimer's disease." (PMID 34101779, 2021). "Chungkookjang traditionally made in Sunchang, Chonbuk-Do, Korea, has been reported to promote insulin sensitivity and subsequently to protect against type 2 diabetes and Alzheimer’s disease progression." (PMID 33494481, 2021). "The importance of insulin in the normal brain function has been confirmed by evidence that insulin dysregulation plays a role in the pathophysiology of Alzheimer’s disease (AD)." (PMID 34948054, 2021). "The insulin sensitizer metformin is currently being evaluated for use in patients with mild cognitive impairment in a national clinical trial (“Metformin in Alzheimer’s Dementia Prevention [MAP]”; NCT04098666)." (PMID 32226608, 2020).
Alzheimer disease (continued). "Local administration of STZ to the brain was shown to impair glucose metabolism and induce an insulin-resistant brain state, and therefore now is widely used as an animal model for Alzheimer’s disease." (PMID 31858268, 2020). "GSK-3 was extensively reported to play an important role in the neurodegeneration in Alzheimer’s disease and is inactivated by insulin-induced signaling." (PMID 31858268, 2020). "With respect to Alzheimer’s disease, recent results have identified an insulin-degrading enzyme as playing a critical role in removing both excess insulin and amyloid β-protein from the brain." (PMID 32127481, 2020). "Regardless, in the Alzheimer’s disease patient, there appears to be a decrease in both cerebral insulin levels and the expression of the insulin receptor that occurs early in the course of the disease." (PMID 33024433, 2020). "CNS insulin levels are decreased and insulin receptor signalling is dampened in Alzheimer's disease (AD)." (PMID 32704569, 2020). "Amelioration of cerebral amyloid-β expression was revealed in mouse models of Alzheimer's disease treated with intranasal insulin." (PMID 31929603, 2020). "More broadly, insulin and insulin-like growth factor pathways represent targets of active interest in Alzheimer’s disease." (PMID 33426524, 2020). "Alzheimer’s disease is characterized by brain insulin resistance and altered glucose homeostasis and hence also termed as Type 3 diabetes mellitus." (PMID 32903435, 2020). "Almost all the articles about the function of insulin for memory in mammals are involved in the studies of the relationship between type 2 diabetes and Alzheimer’s disease." (PMID 33256267, 2020). "In this project, we are trying to review the articles that discuss the relationship between insulin signaling and Alzheimer's disease (AD)." (PMID 32190448, 2020). "Both Alzheimer’s disease (AD) and type 2 diabetes (T2D) share common pathological features including inflammation, insulin signaling alterations, or vascular damage." (PMID 32264944, 2020). "Aberrant brain insulin signaling plays a critical role in the pathology of Alzheimer’s disease (AD)." (PMID 32903692, 2020). "Here, we review the effects of insulin on hippocampus, a brain area playing a pivotal role in learning and memory and primarily affected in Alzheimer’s disease (AD)." (PMID 31417349, 2019). "Patients with Alzheimer’s disease have increased plasma insulin levels, decreased CSF insulin levels, and thus a reduced CSF-to-plasma insulin ratio." (PMID 31213970, 2019). "We also summarize how insulin can regulate levels of the pathological hallmarks of Alzheimer’s disease, including amyloid beta (Aβ) and tau within each cell type." (PMID 31213970, 2019). "Reduction in brain insulin signaling and/or insulin resistance is a prominent feature of type 2 diabetes mellitus, obesity, Alzheimer’s disease, and Parkinson’s disease." (PMID 30796294, 2019). "This suggests that while insulin signaling is impaired in Alzheimer’s disease, the brain still has the ability to respond to insulin." (PMID 31213970, 2019). "A double blind placebo-controlled study on 25 patients showed that intranasal insulin application improved retainment of verbal information after a delay, as well as attention and functional status of patients with Alzheimer’s disease." (PMID 30795555, 2019). "Nevertheless, alterations in the cerebral glucose utilization as well as defects in insulin transmission have been mainly reported in the early stages of Alzheimer’s disease." (PMID 30781611, 2019). "It has also been shown brain insulin levels and insulin receptor levels and signaling are decreased in Alzheimer’s disease." (PMID 31213970, 2019). "Notable examples are the administration of insulin for the treatment of Alzheimer’s disease and apomorphine for the treatment of Parkinson’s disease." (PMID 30995776, 2019).
Alzheimer disease (continued). "Clinical trials have also shown that intranasal insulin elicits beneficial cognitive effects in patients with Alzheimer’s disease." (PMID 30796294, 2019). "In this sense, alterations in the insulin–central nervous system axis and brain glucose metabolism observed in T2DM patients are associated with neuronal death and with the progression of Alzheimer’s disease (AD)." (PMID 31072002, 2019). "Due to the data supporting a role for CNS insulin resistance in Alzheimer’s disease, efforts have been made to investigate the transport of insulin in Alzheimer’s disease compared to ‘healthy’ aging." (PMID 31213970, 2019). "Intranasal (IN) insulin has been shown to improve memory in healthy humans and in a clinical trial to treat patients with Alzheimer’s disease, IN insulin improved cognitive function and preserved metabolic integrity." (PMID 30796294, 2019). "Pre-clinical studies have shown that intranasal insulin is neuroprotective in models of Alzheimer’s disease, Parkinson’s disease, and traumatic brain injury." (PMID 30796294, 2019). "The impact of insulin on Aβ transport at the BBB has also been investigated in obese mice in the triple-transgenic model of Alzheimer’s disease (3xTg-AD)." (PMID 31213970, 2019). "The correlations between cognitive functions and insulin in this study is in accordance with previous observation in T2D patients with Alzheimer’s disease showing improvements in cognitive functions when improving the insulin sensitivity." (PMID 30400947, 2018). "Recently, nasal administration of insulin showed promising results in clinical trials for the treatment of Alzheimer’s disease." (PMID 29543755, 2018). "This suggests that intranasal insulin administration can be a simple and convenient strategy for the therapy of neurodegenerative disorders such as Alzheimer’s disease which are also accompanied by the impairment of insulin signaling." (PMID 29970188, 2018). "Tissue pPE content is affected by insulin sensitivity and exercise, and is significantly altered in conditions such as Alzheimer’s disease, Down’s syndrome, schizophrenia, and Zellweger syndrome." (PMID 29478028, 2018). "In the APP/PS1 transgenic mice model of Alzheimer disease, glucose tolerance and insulin sensitivity were impaired 6–7 months prior to amyloid plaque pathogenesis and cognitive dysfunction." (PMID 30153273, 2018). "This suggests that Alzheimer’s disease is therefore the result of localized insulin resistance leading some scientists to refer to it as type 3 diabetes." (PMID 30271665, 2018). "Rats intracerebroventricularily (icv) treated with streptozotocin (STZ), shown to generate an insulin resistant brain state, were used as an animal model for the sporadic form of Alzheimer’s disease (sAD)." (PMID 29867451, 2018). "Intranasal insulin at a low dose (20–40 IU daily for 4 months) has also been shown to improve memory and cognition in patients with Alzheimer's disease." (PMID 30515210, 2018). "Some studies claim that insulin is correlated to the neurological disorders in including Alzheimer's disease and bipolar disorder." (PMID 30774812, 2018). "One example is that of HT, which was able to restore proper insulin signaling in an in vitro model of Alzheimer’s disease (AD)." (PMID 29891766, 2018). "Recent studies on Alzheimer’s disease report defects in the expression of insulin, its receptors, and insulin-like growth factor." (PMID 30271665, 2018). "Alzheimer’s disease has been called “type 3 diabetes” because of the close link between diabetes mellitus and the potential pathophysiological mechanism of brain insulin resistance leading to its development." (PMID 30262775, 2018). "The insulin/insulin-like growth factor 1 (IGF1) signaling pathways are implicated in longevity and in progression of Alzheimer’s disease." (PMID 30056117, 2018).
Alzheimer disease (continued). "This device has been used extensively in literature, usually at a dose to of 20IU or 40IU of insulin, and has been shown to elicit beneficial effects on various endpoints, both in healthy persons and patients with Alzheimer's disease." (PMID 28291957, 2017). "The second study showing insulin's effect on brain energetics was a randomized, placebo-controlled study, evaluating memory function of Alzheimer's disease patients after 4 months of treatment with intranasal insulin." (PMID 29085297, 2017). "Other central inflammatory processes, such as Alzheimer’s disease, also leads to the development of insensitivity to insulin actions and defects in learning and memory." (PMID 28677618, 2017). "Probiotic administration of Bifidobacterium for 12 weeks has favorable effects on MMSE score, malondialdehyde, hs-CRP, markers of insulin metabolism, and triglycerides levels in patients with Alzheimer’s disease (AD)." (PMID 29091972, 2017). "Recent evidence reveals that aberrant brain insulin signaling plays an important role in the pathology of Alzheimer’s disease (AD)." (PMID 28382978, 2017). "Adults diagnosed with Alzheimer’s disease displayed improved cognition by a 3-week intranasal insulin detemir therapy." (PMID 27589235, 2016). "Impaired neuronal insulin signaling constitutes a progression factor in the neurodegeneration found in Alzheimer’s disease." (PMID 27639375, 2016). "Brain insulin signaling deficits contribute to multiple pathological features of Alzheimer's disease (AD)." (PMID 27457264, 2016). "Results obtained from preclinical studies and controlled trials on healthy volunteers and individuals with mild cognitive impairment or Alzheimer’s disease have supported the potential of intranasal insulin in improving memory performance." (PMID 26801406, 2016). "It was first proposed as a noninvasive intranasal method for bypassing the blood–brain barrier (BBB) by William H. Frey II and later expanded for the specific use of intranasal insulin to target the brain to treat Alzheimer’s disease and other CNS disorders." (PMID 26933626, 2016). "Insulin signaling is related to tau phosphorylation, an early pathology of Alzheimer's disease; this is complementary to the fact that there are a large number of insulin-sensitive glucose transporters in the medial temporal lobe." (PMID 26881095, 2016). "IIS in the context of Alzheimer’s disease is currently the focus of much investigation with a number of studies investigating the potential of insulin supplementation as a therapeutic since it improves cognitive function." (PMID 26297026, 2015). "Also, it has been described that insulin is one of the molecules that regulate tau protein phosphorylation in neurons, and thus insulin resistance may disrupt this process, causing tau to bind to microtubules, giving rise to the pathogenesis of Alzheimer's disease and dementia." (PMID 26464871, 2015). "Indirectly, low brain insulin levels exacerbate amyloid beta (Aβ) and tau pathology, hallmarks of Alzheimer disease (AD)." (PMID 25071557, 2014). "Conversely, the intranasal application of insulin has been demonstrated to improve cognitive function in patients with minimal impairment or overt Alzheimer’s disease." (PMID 24941010, 2014). "Further, intranasal administration of insulin in patients with Alzheimer’s disease exhibited neuroprotective effects." (PMID 25396726, 2014). "Further, a link between inflammation, neuronal dysfunction and defective insulin signalling in Alzheimer’s disease has been demonstrated." (PMID 25515237, 2014). "An increasing number of studies suggest that insulin plays a role in the pathogenesis of Alzheimer's disease." (PMID 24339978, 2013). "The ViaNase device has been used to deliver nasal insulin in patients with early Alzheimer’s disease (AD), and clinical benefit has been demonstrated." (PMID 23316447, 2013).